FGFR1 (fibroblast growth factor receptor 1)
Diseases named in the same sentence as FGFR1 in open-access papers (continued):
Sharing a sentence is not in itself a finding about the gene and the disease.
pituitary tumor (3 papers, 2014 to 2025). A benign or malignant neoplasm affecting the pituitary gland. "The index kindred’s FGFR1 D129A variant was additionally found in a female South-Asian patient in the pituitary tumour cohort, also in the setting of a prolactinoma." (PMID 40064730, 2025). "The index kindred’s FGFR1 D129A variant was enriched in the pituitary tumour cohort, highlighting a potential association with pituitary tumorigenesis." (PMID 40064730, 2025). "The second FGFR1 variant identified in a patient with pituitary tumour (FGFR1, c.1447 C > T, p.(P483S)) has also been found in individuals with a hypoproliferative pituitary phenotype." (PMID 40064730, 2025). "A further rare missense FGFR1 variant (c.1447 C > T, p.(P483S), allele frequency 0.0007%), was also identified in a patient in the pituitary tumour cohort." (PMID 40064730, 2025). "We identify divergent phenotypes of childhood-onset macroprolactinoma and CPHD in a kindred with a germline FGFR1 variant and demonstrate enrichment of this variant in individuals with pituitary tumours compared to controls." (PMID 40064730, 2025). "Our findings support future work analysing specific variants in FGFR1 that may paradoxically promote pituitary developmental abnormalities and tumorigenesis, potentially providing insight into pituitary tumour pathogenesis." (PMID 40064730, 2025). "On the other hand, it has also been determined that cytoplasmic FGFR1 immunoreactivity was inversely correlated with maximum pituitary tumor diameter." (PMID 25505910, 2014). "Furthermore, FGFR1 has been proposed as a candidate marker of pituitary tumors together with FGF2 and pituitary tumor transforming gene (PTTG); indeed, the FGF2 receptor FGFR1 was found to be highly expressed in pituitary tumors compared to the normal gland." (PMID 25505910, 2014).
pulmonary arterial hypertension (3 papers, 2017 to 2021). Pulmonary arterial hypertension (PAH) is a group of diseases characterized by mean pulmonary artery pressure >20 mmHg and elevated pulmonary arterial resistance leading to right heart failure. "In humans, it was shown that APLN indirectly regulates the expression of FGF2 and FGFR1 in pulmonary arterial hypertension via its microRNA mediators miR-424 and miR-503." (PMID 32252341, 2020).
renal agenesis (3 papers, 2015 to 2024). Renal agenesis (RA) is a form of renal tract malformation characterized by the complete absence of development of one or both kidneys (unilateral RA or bilateral RA respectively), accompanied by absent ureter(s). "We describe for the first time two cases in which KS was suspected during fetal life because of the family context and malformation detection by fetal ultrasound: syndactyly or unilateral renal agenesis in subjects with respectively FGFR1 and KAL1 mutations." (PMID 26051373, 2015).
rheumatoid arthritis (3 papers, 2010 to 2022). A chronic, systemic autoimmune disorder characterized by inflammation in the synovial membranes and articular surfaces. "Finally, we identified 146 likely causal genes for rheumatoid arthritis, including CD4, FGFR1, and KDR, which have been reported as high risk factors by recent studies." (PMID 20727150, 2010).
salivary gland cancer (3 papers, 2010 to 2022). A primary or metastatic malignant neoplasm that affects the major or minor salivary glands. "Salivahas significantly higher levels of fibroblast growth factor 2 (FGF2) and fibroblast growth factor receptor 1 (FGFR1) in patients withsalivary gland tumours, making it a possible biomarker for the early detection of salivary gland cancers." (PMID 37693919, 2022). "In malignant salivary gland tumors, theoverexpression of FGF2 and FGFR-1 facilitates neoplastic progression." (PMID 20379686, 2010).
small cell carcinoma (3 papers, 2018 to 2025). A neuroendocrine carcinoma composed of small malignant cells which are often said to resemble "oat cells" under the microscope. "Amplification and dysregulation of FGR family and specifically FGFR1 has been observed in small cell carcinoma and other forms of cancer." (PMID 29755656, 2018). "FGFR1-amplification has been observed in up to 20% of pulmonary SCCs and less frequently in ADCs and small-cell carcinomas." (PMID 29899852, 2018). "Therefore, we selected the DMS114 cell line, a small cell carcinoma-derived cell line, known to have an amplification at the genomic locus harbouring FGFR1 gene, to perform growth experiments comparing the two Spry4 variants." (PMID 40806483, 2025).
stem cell leukemia/lymphoma (3 papers, 2022 to 2025). "Stem cell leukemia/lymphoma (SCLL) exhibits distinct clinical and pathological features, characterized by chromosomal translocations involving the FGFR1 gene at chromosome 8p11." (PMID 35574218, 2022).
tooth agenesis (3 papers, 2014 to 2025). A tooth disease characterized by failure to develop one or more missing teeth. "Using whole-exome sequencing of a Han Chinese family with non-syndromic tooth agenesis, a rare mutation in FGFR1 (NM_001174063.2: c.103G > A, p.Gly35Arg) was identified as causative and confirmed by Sanger sequencing." (PMID 37833774, 2023). "The genetic basis of tooth agenesis is well-established, with several genes identified as controlling factors, namely MSX1, PAX9, AXIN2, EDA, IRF6, FGFR1, and WNT10A." (PMID 40040530, 2025).
alopecia (2 papers, 2024 to 2025). Hair loss usually from the scalp. "ECCL is characterized by ocular anomalies, skin lesions (e.g., alopecia, naevus psiloliparus, nodular skin tags, and aplastic scalp defects), and central nervous system anomalies and caused by the postzygotic somatic activating variants p.(Asn546Lys) and p.(Lys656Glu) in FGFR1." (PMID 38265560, 2024).
anaplastic thyroid carcinoma (2 papers, 2015 to 2019). "Interestingly, the gene fusion WHSC1L1::FGFR1 was detected in one patient each from the AMP and the OCA cohort (adenocarcinoma of pancreatobiliary type and anaplastic thyroid carcinoma, respectively)." (PMID 31491926, 2019).
astrocytic neoplasm (2 papers, 2022 to 2025). "In astrocytic tumors, FGFR1 expression increases with malignancy, with lower-grade tumors showing weaker expression." (PMID 40393028, 2025).
B-cell lymphoblastic leukemia (2 papers, 2019 to 2022). "In summary, miR-17-92 is a downstream effector of fibroblast growth factor receptor 1 (FGFR1) in BCR-FGFR1-driven B-cell lymphoblastic leukemia." (PMID 30854399, 2019).
bipolar disorder (2 papers, 2012 to 2020). A disorder of the brain that causes unusual shifts in mood, energy, activity levels and the ability to carry out day-to-day tasks. "Two recent candidate genes, ErbB3 and Fgfr1, are growth factors whose mRNA levels have been found to be altered in the leukocytes of patients that are affected by bipolar disorder in a depressive state." (PMID 22989054, 2012). "In a postmortem study, it was found that FGF-2 and FGFR1 levels did not change in the brain in bipolar disorder patients." (PMID 32283906, 2020).
cardiomyopathies (2 papers, 2017 to 2025). "Although no studies have specifically investigated the relationship between FGFR2 and TLR4, research has demonstrated that high glucose -induced activation of FGFR1 is mediated by TLR4 and c-Src in the context of cardiomyopathy." (PMID 40791737, 2025).
chronic kidney disease (2 papers, 2013 to 2020). Impairment of the renal function secondary to chronic kidney damage persisting for three or more months. "Rats with chronic renal failure had low klotho and FGFR1 mRNA and protein levels in the parathyroid." (PMID 32570711, 2020). "Therefore, parathyroid FGFR1 and klotho expression is decreased in experimental SHP and in end-stage renal disease patients, and this may lead to resistance of the parathyroids to FGF23 in SHP." (PMID 32570711, 2020).
chronic obstructive pulmonary disease (2 papers, 2015 to 2019). A chronic and progressive lung disorder characterized by the loss of elasticity of the bronchial tree and the air sacs, destruction of the air sacs wall, thickening of the bronchial wall, and mucous accumulation in the bronchial tree. "Furthermore, chronic obstructive pulmonary disease (COPD) is associated with enhanced bronchial expression of FGF1 and FGFR1 as well as FGF2." (PMID 26138239, 2015).
cognitive decline (2 papers, 2020 to 2021). "Of interest in the study of neurological disorders with cognitive decline is the recent demonstration by proximity ligation assay of receptor complexes involving fibroblast growth factor receptor 1 (FGFR1) and serotonin 5HT1A receptor in hippocampal astrocytes." (PMID 34445362, 2021).
coronary artery disease (2 papers, 2021 to 2024). "In a drug-target analysis for coronary artery disease (CAD), including a proteome-wide application, we identified three potential drug targets, PCSK9, COLEC11 and FGFR1 for CAD." (PMID 39025905, 2024).
diffuse intrinsic pontine glioma (2 papers, 2021 to 2022). A neuroglial tumor that arises from the middle portion of the brain stem. "In diffuse intrinsic pontine glioma (DIPG—also called diffuse midline gliomas), H3K27M mutations, as well as ACVR1, FGFR1, MET, and PIK3CA mutations, were clonal." (PMID 33673104, 2021).
dwarfism (2 papers, 2015 to 2023). "FGFR germline mutations (activating) can cause skeletal disorders, primarily dwarfism (generally mutations in FGFR3) and craniofacial malformation syndromes (usually mutations in FGFR1 and FGFR2)." (PMID 26224133, 2015). "FGFR germline mutations (activating) can cause skeletal disorders, primarily dwarfism (generally mutations in FGFR3), and craniofacial malformation syndromes (usually mutations in FGFR1 and FGFR2); intriguingly, some of these activating FGFR mutations are also seen in human cancers." (PMID 26224133, 2015).
emphysema (2 papers, 2019 to 2022). "The purpose of this study was to evaluate PD-L1, FGFR1, PIK3CA, PTEN, and p16 expression in SCC associated with emphysema and COPD." (PMID 31481045, 2019). "Therefore, further studies are needed to clarify the crosstalk between these receptors, and to explore whether FGF10 attenuates endothelial apoptosis and emphysema through pathways other than FGFR1." (PMID 36183124, 2022). "We used the murine emphysema model and in vitro studies to determine the protective and reparative role of FGF10/FGFR1." (PMID 36183124, 2022). "Importantly, administration of FGF10 rescued glycocalyx impairment and emphysema in a murine model of COPD, probably through a FGFR1/ERK/SOX9/HS6ST1 loop in endothelial cells." (PMID 36183124, 2022). "There were no other significant associations between PD-L1, FGFR1, PIK3CA, PTEN, and p16 expression and total/local severity of emphysema or presence of COPD/GOLD stage." (PMID 31481045, 2019).
endothelial dysfunction (2 papers, 2023 to 2026). In vascular diseases, endothelial dysfunction is a systemic pathological state of the endothelium (the inner lining of blood vessels) and can be broadly defined as an imbalance between vasodilating and vasoconstricting substances produced by (or acting on) the endothelium. "Mechanistically, transforming growth factor-β (TGF-β) activated the FGFR1-ERK-YAP1 signaling cascade, which drove endothelial-to-mesenchymal transition (EndMT), inflammatory responses, and endothelial dysfunction." (PMID 42051262, 2026). "Meanwhile, in vitro knockdown of FGFR1 by siRNA activated ROCK2, leading to endothelial dysfunction with increased adhesive properties and permeability in TNFα-treated HUVECs." (PMID 36969192, 2023).
eosinophilic disorders (2 papers, 2024 to 2025). "Cytogenetic testing was negative for PDGFRA, PDGFRB, and FGFR1 mutations, ruling out clonal eosinophilic disorders." (PMID 40823575, 2025).
Glucose intolerance (2 papers, 2022 to 2024). Glucose intolerance (GI) can be defined as dysglycemia that comprises both prediabetes and diabetes. "Lig1 (DNA ligase 1) expression was negatively correlated with body mass, while Fgfr1 expression was positively correlated with both glucose intolerance and body mass." (PMID 36424602, 2022).
hemangioblastoma (2 papers, 2016 to 2025). "Mutations resulting in FGFR1 loss were observed in a subset of hemangioblastoma samples analyzed using single-nucleotide polymorphism microarrays and droplet digital PCR." (PMID 40393028, 2025). "The association of FGFR1 with aggressive behavior aligns with its absence in histologically benign hemangioblastomas, although differences in histogenesis complicate direct comparisons." (PMID 40393028, 2025). "In this study, formalin-fixed, paraffin-embedded (FFPE) samples obtained from both VHL-related and sporadic hemangioblastoma patients were utilized for immunohistochemical characterization of FGFR1–4." (PMID 40393028, 2025).
Hypercholesterolemia (2 papers, 2018 to 2020). An increased concentration of cholesterol in the blood. "We detected hypomethylation in FGF19 and FGFR1 genes in leukocytes DNA of obese patients with hypercholesterolemia." (PMID 33028190, 2020). "The present study demonstrated that hypercholesterolemia increased the release of inflammatory cytokine TNF-α and then promoted intraplaque angiogenesis by enhancing VEGF-A/VEGFR-2 and FGF-2/FGFR-1 expression." (PMID 30125282, 2018).
Hypoglycemia (2 papers, 2013 to 2022). A decreased concentration of glucose in the blood. "Once activated, FGFR1 exerts positive effects on hypoglycemia and lipid reduction by activating the AKT, AMPK, and NF-κB signaling pathways." (PMID 35935824, 2022).
in situ carcinoma (2 papers, 2015 to 2020). A malignant epithelial neoplasm which is confined to the epithelial layer without evidence of further tissue invasion. "In our series, high FGFR1 expression was observed in about 11% of tested cases with hypopharynx and larynx SCCs." (PMID 32326908, 2020).
intracranial hemorrhage (2 papers, 2024). Bleeding within the SKULL, including hemorrhages in the brain and the three membranes of MENINGES. "We investigate the frequency of spontaneous intracranial hemorrhage and link these events to their genetic mutations, specifically looking for any statistically significant correlation between hemorrhage and FGFR1 mutations." (PMID 38903142, 2024). "This case study discusses DNETs that can develop into malignancies, have FGFR1 mutations, and induce symptomatic intracranial hemorrhage." (PMID 39114195, 2024). "Our case series highlights this link between the FGFR1 mutation and spontaneous intracranial hemorrhage in pediatric LGGs." (PMID 38903142, 2024). "Statistical analysis found a significant association between FGFR1 and spontaneous intracranial hemorrhage (P-value = < .0001)." (PMID 38903142, 2024). "Furthermore, we present any cases in which a patient with an FGFR1 mutation experienced spontaneous intracranial hemorrhage, with the hopes of contributing to the current literature on this potential novel risk factor in pediatric LGG patients." (PMID 38903142, 2024). "However, a recent study proposing the FGFR1 mutation as a potential novel risk factor for spontaneous intracranial hemorrhage in pLGG patients warrants further studies." (PMID 38903142, 2024). "A recent study highlighted a link between FGFR1 mutations and spontaneous intracranial hemorrhage (ICH), demonstrating that all patients with an FGFR1 alteration experienced hemorrhage at some point during their course of treatment." (PMID 38903142, 2024).
invasive carcinoma (2 papers, 2012). A carcinoma that is not confined to the epithelium, and has spread to the surrounding stroma. "In this study we have shown that FGFR1 amplification is more frequent in invasive carcinoma than in pure DCIS, and in the invasive components of tumors with invasive and DICS components." (PMID 22863309, 2012). "The frequency of FGFR1 amplification was higher in invasive carcinomas than in pure DCIS (12.5% vs. 6.0%, P = 0.020)." (PMID 22863309, 2012). "We measured the HER2, C-MYC, CCND1 and FGFR1 amplification status in pure DCIS, DCIS associated with invasive carcinomas, and invasive carcinomas." (PMID 22863309, 2012). "The rate of amplification of FGFR1 was higher in invasive carcinomas than in the pure DCIS, but the opposite was true for HER2 amplification." (PMID 22863309, 2012). "In survival analyses, FGFR1 amplification was found to be an independent prognostic factor for poor disease-free survival for all patients with invasive carcinoma and for the hormone receptor-positive subgroup." (PMID 22863309, 2012). "Conversely, the FGFR1 amplification frequency tended to be higher in invasive carcinoma than in pure DCIS (15.6% vs. 6.8%, P = 0.056)." (PMID 22863309, 2012). "However, FGFR1 amplification was more frequent in invasive carcinomas than in pure DCIS, and in the invasive components of the same tumors." (PMID 22863309, 2012). "In this study, we compared the gene amplification frequencies of HER2, C-MYC, CCND1 and FGFR1 in a relatively large series of pure DCIS, DCIS associated with invasive carcinoma, and invasive carcinomas, to investigate the role of gene amplification in the progression of DCIS to invasive carcinomas." (PMID 22863309, 2012). "In summary, we have studied the amplification frequencies of HER2, C-MYC, CCND1 and FGFR1 in a large series of pure DCIS, DCIS associated with invasive carcinoma, and invasive carcinomas, to investigate the role of gene amplification in the progression of DCIS to invasive carcinoma." (PMID 22863309, 2012). "In our study, FGFR1 amplification was more frequent in invasive carcinoma than in pure DCIS, and tended to be higher in invasive carcinomas than in pure DCIS in the high-grade tumors." (PMID 22863309, 2012). "CCND1 amplification was correlated with HER2 and FGFR1 amplification in invasive carcinoma, but not in the pure DCIS." (PMID 22863309, 2012).
laryngeal carcinoma (2 papers, 2021 to 2023). Carcinoma that arises from the laryngeal epithelium. "Katarzyna etc. reported that FGFR1 and 3 expression is associated with regulatory PI3K/AKT kinase activity and promotes invasion and prognosis of human laryngeal cancer." (PMID 34294681, 2021).
lipodystrophy (2 papers, 2012 to 2022). A congenital or acquired disorder characterized by abnormal loss or redistribution of the adipose tissue in the body. "Proximally, β-klotho and FGFR1 mRNA were expressed normally in lipodystrophy WAT." (PMID 22792234, 2012).
male infertility (2 papers, 2015 to 2021). The inability of the male to effect fertilization of an ovum after a specified period of unprotected intercourse. "Several human genes are known with mutations causing male infertility (AR; AZF gene families; CFTR, DM-1, DNAH gene family, FGFR1, FSHR, INSL3, KAL-1, LGR8-GREAT, LHR, POLG)." (PMID 26097523, 2015).
microtia (2 papers, 2020 to 2023). "Together with our proband, we therefore recommend consideration of FGFR1 genetic testing in patients presenting a Goldenhar-like syndrome or microtia to aid in diagnosis and expand the mutation spectrum of FGFR1-associated TA." (PMID 37833774, 2023).
myelofibrosis (2 papers, 2022 to 2023). A partial or complete replacement of the bone marrow stroma by fibrous tissue. "Three genes implicated in myelofibrosis were found to be overexpressed in HLC: FGF2 (fibroblast growth factor-2; 500-fold), its receptor FGFR1 (50-fold), and TGFB1 (tumor growth factor ß1; 16-fold)." (PMID 35476232, 2022).